ENSG00000251184 (novel protein)
Gene: Protein-coding gene on chromosome 9 (128,941,478 to 128,957,021, forward strand). Ensembl gene ENSG00000251184.
Genetic constraint (gnomAD): Loss-of-function variants: 4 observed, 9.09 expected, observed/expected ratio (o/e) 0.44, 90% interval 0.22 to 1.01. That is too few expected variants to judge how well the gene tolerates losing a copy. Missense variants: 36 observed, 45.7 expected, observed/expected ratio (o/e) 0.79, 90% interval 0.6 to 1.04. Synonymous variants: 12 observed, 17 expected, observed/expected ratio (o/e) 0.71, 90% interval 0.45 to 1.14.